RXYLT1 (ribitol xylosyltransferase 1)
Description:
Acts as a UDP-D-xylose:ribitol-5-phosphate beta1,4-xylosyltransferase, which catalyzes the transfer of UDP-D-xylose to ribitol 5-phosphate (Rbo5P) to form the Xylbeta1-4Rbo5P linkage on O-mannosyl glycan (Probable). Participates in the biosynthesis of the phosphorylated O-mannosyl trisaccharide (N-acetylgalactosamine-beta-3-N-acetylglucosamine-beta-4- (phosphate-6-)mannose), a carbohydrate structure present in alpha-dystroglycan (DAG1), which is required for binding laminin G-like domain-containing extracellular proteins with high affinity (Probable).
Synonyms: TMEM5; HP10481; MDDGA10
Tractability: Antibody: its Gene Ontology location is reachable by antibodies, with high confidence; UniProt predicts a signal peptide or a membrane-spanning region.
Gene: Protein-coding gene on chromosome 12 (63,779,833 to 63,809,792, forward strand). Ensembl gene ENSG00000118600.
Subcellular location: Golgi apparatus membrane
Subcellular location (Human Protein Atlas): Golgi apparatus; Nucleoplasm
Pathways (Reactome):
Metabolism of proteins: Matriglycan biosynthesis on DAG1
Gene Ontology:
Molecular function: protein binding; ribitol beta-1,4-xylosyltransferase activity
Biological process: protein O-linked glycosylation via mannose; protein O-linked glycosylation
Cellular component: catalytic complex; Golgi apparatus; Golgi membrane; plasma membrane
Genetic constraint (gnomAD): Loss-of-function variants: 41 observed, 48.79 expected, observed/expected ratio (o/e) 0.84, 90% interval 0.65 to 1.09. The upper end of that interval is the gene's LOEUF score, 1.09, which puts it in group 4 of 6, group 1 being the genes least tolerant of losing a copy. Missense variants: 491 observed, 509.34 expected, observed/expected ratio (o/e) 0.96, 90% interval 0.89 to 1.04. Synonymous variants: 161 observed, 191.14 expected, observed/expected ratio (o/e) 0.84, 90% interval 0.74 to 0.96.
Gene-disease validity (ClinGen):
ClinGen rates the evidence that RXYLT1 causes each of these diseases.
muscle-eye-brain disease (autosomal recessive): Definitive.
Homologues: Orthologues: chimpanzee RXYLT1 (99% identical), macaque RXYLT1 (98% identical), dog RXYLT1 (91% identical), pig RXYLT1 (89% identical), rat Rxylt1 (85% identical), mouse Rxylt1 (83% identical), rabbit RXYLT1 (80% identical), guinea pig RXYLT1 (75% identical), tropical clawed frog rxylt1 (61% identical), zebrafish rxylt1 (54% identical).
Diseases named in the same sentence as RXYLT1 in open-access papers:
RXYLT1 is named in the same sentence as 16 diseases in open-access papers, as found by Europe PMC text mining. Sharing a sentence is not in itself a finding about the gene and the disease. The quoted sentences say what the papers report.
muscular dystrophy (4 papers, 2016 to 2022). Muscular dystrophy (MD) refers to a group of more than 30 genetic diseases characterized by progressive weakness and degeneration of the skeletal muscles that control movement. "RXYLT1's glycosylation target, α-dystroglycan, is known to be associated with certain muscular dystrophies." (PMID 33102519, 2020). "Among them, two examples were selected to illustrate age-related differential exon usage: SMIM11A mRNA (Small Integral Membrane Protein 11A, of unknown function) and RXYLT1 mRNA (Ribitol Xylosyltransferase 1, associated with Walker–Wahlburg syndrome and muscular dystrophy–dystroglycanopathy)." (PMID 33795677, 2021).
soft tissue tumor (1 paper, 2022). "Although there is no sufficient evidence to confirm the relationship between EWS and RXYLT1, we figure that RXYLT1 may affect the occurrence of EWS in that EWS is a bone and soft tissue tumor." (PMID 35719404, 2022).
RXYLT1 also shares sentences with these, for which no sentence is quoted: tumor (6 papers); dystroglycanopathies (4); Walker-Warburg syndrome (4); prostate carcinoma (3); cancer (2); breast carcinoma (1); colon cancer (1); congenital muscular dystrophy (1); gastric cancer (1); Hydrocephalus (1); liver cancer (1); Mental Retardation (1); orofacial cleft (1); psoriasis (1).